IL6 (interleukin 6)
Diseases named in the same sentence as IL6 in open-access papers (continued):
Sharing a sentence is not in itself a finding about the gene and the disease.
Obesity (continued). "In addition, systemic oxidative stress induced by IR and obesity may activate a downstream inflammatory cascade, and patients with MetS have elevated levels of various inflammatory markers, including C-reactive protein (CRP) and interleukin (IL)-6." (PMID 40095232, 2025). "In addition, muscle IL-6 modulates the immune response by inhibiting TNF-α production and stimulating anti-inflammatory cytokines such as IL-10 and IL-1ra, which favors the reduction of chronic low-grade inflammation observed in pathologies such as obesity and type 2 diabetes." (PMID 40648864, 2025). "In contrast, pathophysiological states—including sedentary lifestyle, obesity, chronic inflammation, and glucocorticoid excess—favor a shift toward a proinflammatory and catabolic myokine profile, characterized by increased levels of myostatin, non-muscle-derived IL-6, and TNF-α." (PMID 40648864, 2025). "The IL6/ADPN/HMGB1 axis was differentially expressed in human subepicardial tissue and blood samples, and was an independent factor in patients with CAD, which may partly explain the obesity paradox in patients that are overweight or obese, particularly among those who develop symptomatic CAD." (PMID 38601146, 2024). "Previous studies have reported that increased IL-6 levels are strongly associated with reduced exercise capacity and more severe symptoms of exercise intolerance, which are typically present in patients with preserved LVRF and obesity; in contrast, we did not observe these associations." (PMID 38892570, 2024). "In the context of RA, obesity may contribute to its pathogenesis by fostering a chronic pro-inflammatory state, characterized by elevated levels of tumor necrosis factor-α (TNF-α) and interleukin-6 (IL-6), which in turn stimulate autoantibody production and inflammatory cell activation." (PMID 37474953, 2023). "In addition, antibody neutralization of CD44 reduces obesity-induced adipose tissue inflammation, as demonstrated by decreased expression of immune cell markers (CD68, F4/80, CD3e, and CD19), proinflammatory cytokines (TNF-α, IL-1β, IL-6, and IFN-γ), and monocyte chemoattractant protein-1 (MCP-1)." (PMID 37383542, 2023). "In addition, the mRNA expression of pro-inflammatory cytokines TNFα, IL-6, and IL-1β was significantly higher in HFD-fed animals in comparison to STD-fed animals, suggesting that type I gustatory cells can be differentiated into M1-like phenotype of macrophages in obesity." (PMID 37373472, 2023). "Obesity and MetS could promote BC proliferation, invasion and progression through low chronic inflammation and imbalance of tumor microenvironment which result in increased production of fibroblasts, T cells and pro-inflammatory cytokines such as TNF-a, IL-6, and IL-8." (PMID 38040773, 2023). "Also we did not measure sarcopenic obesity related pro-inflammatory cytokines such as interleukin 6 and tumor necrosis factor which could lead IR." (PMID 34983489, 2022). "Moreover, IL-6 and IL-1β transcription in mesenteric and periovarian WAT was greatly decreased in both PCOS-like and obese rats after EA treatment, similar to trends in inguinal WAT, indicating that the improvement of chronic inflammation in WAT played a major role in EA-affected obesity." (PMID 35436959, 2022). "Given that agents targeting IL‐6 signaling have been used in global inflammation disorders, targeting CD146 to stimulate IL‐6 signaling in ATMs presents a promising alternative strategy for obesity and other metabolic syndromes that might be used to influence IL‐6 signaling effects." (PMID 35258174, 2022). "Moreover, obesity and non-cardiovascular inflammatory diseases considerably interfere with serum IL-6 levels, which may lead to a confusing bias." (PMID 36028849, 2022).
Obesity (continued). "Numerous factors could elucidate the relationship between obesity and anxiety, one of which is immune-inflammatory stimulation, as both conditions increase inflammatory biomarkers, such as C-reactive protein (CRP), interleukin-6 (IL-6) and tumour necrosis factor-alpha (TNF-α)." (PMID 33962601, 2021). "Thus our data indicated that the IL-6/IDO1 axis may play a pathogenetic role in a chronic, low-grade inflammation condition, and, perhaps most importantly, IL-6R blockade may be considered a valid option for obesity treatment." (PMID 34394118, 2021). "Besides, recent studies suggested that obesity related-excess adipose tissue could promote the neoplasia and progression of tumor through adipose tissue inflammation (circulating cytokines such as TNF-α and IL-6)." (PMID 35096970, 2021). "This unique finding suggests the IL-6/IL-10 cytokine axis observed only in females may account for their lower weight gain compared to males during the period of DIO, and this strongly suggests sex as an important biological variable to be considered in obesity research." (PMID 34439950, 2021). "CATi and IL-6 measurement at admission and the use of a composite score could help physicians to better identify such patients with a potentially severe and lethal course, irrespective of obesity and consider early preventive anti-inflammatory therapies." (PMID 34384426, 2021). "Cardiac adipose tissue index and IL-6 determination at admission could help physicians to better identify diabetic patients with a potentially severe and lethal short term course irrespective of obesity." (PMID 34384426, 2021). "Consequently, CATi and IL-6 determination at admission could help physicians to better identify diabetic patients with a potentially severe and lethal course, irrespective of obesity." (PMID 34384426, 2021). "However, unlike normal aging, obesity is associated with a higher RDW, perhaps because elevations in RDW are associated with metabolic syndrome rather than senescence, and also higher IL-1RA, IL-6, IL-17 and VEGF." (PMID 32027700, 2020). "Although the mechanism for the increase in circulating zonulin in obesity is not fully eluded, it is proposed that inflammatory cytokines such as TNFα, and IL-6 produced by adipose tissue may trigger zonulin release, further increasing intestinal permeability, allowing more LPS into circulation." (PMID 31114691, 2019). "However, elevated levels of IL-6 are reported in a study excluding patients with a body mass index (BMI) > 25, which gave rise to the conclusion that the changes of IL-6 did not seem to be related to obesity." (PMID 31908647, 2019). "However, elevated IL-6 levels may be more detrimental in combination with low physical activity rather than simply obesity alone." (PMID 30875990, 2019). "Furthermore, while obesity increased IL‐6 in WT, this increase did not occur in p50−/−." (PMID 30251338, 2018). "Moreover, increased intestinal inflammatory gene expression of TNF-α, IL-6, ICAM and PTGS-2 was found in insulin-resistant obese patients compared to non-insulin-resistant obese patients, suggesting that intestinal inflammation is involved in diabetes during obesity." (PMID 27620343, 2017). "However, on the stage of extremely obesity or diabetes, dysfunctional adipocytes could increase the pro‐inflammatory factors secretion, such as TNF‐α and IL‐6 that modulate an angiogenesis response in adipose tissue 43, 44 and could be a primary contributor of angiogenesis." (PMID 28631352, 2017). "Therefore, in the obesity-related cancer environment where many cytokines show altered profiles, angiogenesis factors (i.e., EGF, VEGF, and PAI-1) and inflammatory mediators (i.e., IL-1, IL-6, TNF-α, and leptin) are thought to cultivate a favorable environment for neoplastic cell growth." (PMID 26794215, 2016).
Obesity (continued). "Furthermore, inflammatory markers such as C-reactive protein and IL-6 are predictive of diabetes even in nonobese subjects, suggesting that inflammation, not obesity per se, may be the major culprit in disease pathogenesis." (PMID 26146464, 2015). "It is also possible that since both CRP and IL-6 are nonspecific indicators of systemic inflammation, infections, injury, obesity or proinflammatory chronic conditions, or other sources of inflammation may have accentuated or masked the effects of traffic pollutant exposure." (PMID 25685160, 2015). "The mechanisms relating N-acetyl glycoproteins to obesity and IPB, remain unclear; however, it is widely reported that high levels of adipose tissue can lead to systemic inflammation through release of cytokines such as interleukin-6, which could lead to an acute phase response." (PMID 25012562, 2014). "In addition, increases in serum inflammatory markers such as interleukin-6 (IL-6) and C-reactive protein (CRP) have been shown to exacerbate cognitive decline in older adults with metabolic syndrome, a condition defined by cooccurring obesity, hypertension, dyslipidemia, and hyperglycemia." (PMID 22461977, 2012). "Nevertheless, in people with type 2 diabetes, the circulating p- IL-6 concentration is correlated with adipose tissue mass, rather than with whole-body insulin sensitivity, suggesting that IL-6 may be a marker of obesity without any direct contribution to the development of insulin resistance." (PMID 20529356, 2010). "Higher IL-1β, IL-6, IFN-γ and TNF-α levels were observed in the subgroups with obesity than in the normal weight subgroups, regardless of gender." (PMID 41602164, 2026). "Similar low‐frequency EPS (1 Hz, 30 V, 2 ms) lasting 48 h induced IL6 but not IL8 gene expression in myotubes derived from lean donors and donors with obesity." (PMID 40923494, 2026). "Studies have demonstrated that individuals with obesity exhibit significantly higher plasma concentrations of CRP and IL-6 compared to those with overweight, independent of age, sex, and metabolic comorbidities." (PMID 40868054, 2025). "In obesity, a noninfectious inflammatory disease, UBE2M contributes to elevated secretion of the inflammatory cytokines IL-1β, IL-6, and TNF, while its absence leads to reduced levels of these cytokines." (PMID 39675717, 2025). "Independent of obesity, PCOS is marked by low-grade inflammation: circulating levels of TNF-α, IL-6, IL-8 and C-Reactive Protein are elevated relative to controls." (PMID 40694958, 2025). "Sixth, This study only examined the relationship between IL-6, TNF-α, and IL-2 levels and psychiatric symptoms and obesity, without testing other factors, particularly C-reactive protein (CRP) and interleukin-10 (IL-10)." (PMID 40791199, 2025). "Elevated levels of inflammatory markers such as C-reactive protein (CRP), fibrinogen, TNF-α, and IL-6 have been observed in OSA patients, independent of obesity." (PMID 40428013, 2025). "Compared with the use of metformin, Qu (300 mg/kg), can assist metformin in reducing the levels of serum IL-6 and TNF-α, relieving the inflammatory response of obesity, and has good safety, with no obvious organ toxicity." (PMID 39712006, 2024). "No statistical differences were found in IL-6 and TNF-α between groups of children with obesity vs. those of normal weight or in children with vs. those without MetS." (PMID 39771030, 2024). "On the other hand, the mRNA levels of Il6 and Il1b did not elevate in the WAT of animals with obesity." (PMID 39004641, 2024). "The cytokine production capacity of children with obesity was higher for TNF, IL-1β, IL-6, IL-10, IL-1Ra, IL-12p70, MCP-1, RANTES, and MIP1α, but not IL-8, indicating an overall hyperresponsive state compared to controls." (PMID 38741712, 2024). "Nevertheless, we also observed changes in cytokine release in monocytes from donors with obesity after LPS i.e. TLR4 stimulation, whereby TNF, IL-6, and IL-1 were not affected, while IL-8 was increased." (PMID 39050851, 2024).
Obesity (continued). "Moreover, oral gavage with 109 CFU/200 μL A. muciniphila reverses high fat obesity through improving intestinal barrier integrity, inflammation, energy balance, and triglyceride and glucose in the blood, which also suppresses mRNA expression of Tlr4 and Il-6 but not Tnf-α in adipose tissues." (PMID 37287985, 2023). "In patients without DM or obesity severe pneumonia, NLR, CRP, IL-6, insulin resistance indices, and hyperglycemia during hospitalization were associated with longer hospitalization." (PMID 37515156, 2023). "A meta-analysis of the subjects’ inflammatory response data showed that training improved IL-6 levels and significantly reduced CRP levels in adolescents with obesity, but training did not improve TNF-α levels in adolescents with obesity." (PMID 36293806, 2022). "The circulating levels of IL-6, IL-8, and tumour necrosis factor alpha (TNF-α) distinguished patients with obesity and lean controls but did not distinguish patients with and without NASH." (PMID 35887177, 2022). "In the not pregnant setting, obesity induces insulin resistance and T2DM through the release of cytokines such as TNFα and IL-6." (PMID 35348641, 2022). "By contrast, some reports have noted a negative correlation between cytokine levels (IL-6, adiponectin, and TNF-α) and obesity, suggesting that inflammation is a consequence of obesity rather than a contributing factor." (PMID 35682832, 2022). "A systematic review with a meta-analysis of subjects with overweight or obesity reported that supplementation with vitamin D did not decrease CRP, TNF-α, or IL-6 levels." (PMID 35893929, 2022). "It is not yet known whether the expression of IL6 mediated by Wnt5a/JNK is an extended mechanism to adipocytes of other species, including the mouse which is a model in many studies on the role of adipocytes in obesity and the associated pathologies to this disease." (PMID 35111744, 2021). "In terms of the impact of HFCD on obesity, inflammatory markers, and T2DM, WAT produces elevated inflammatory cytokines, including TNF-α and IL-6, which exert negative systemic and local effects on WAT and organ functions." (PMID 34037093, 2021). "Finally, RNA-seq results showed that the transcription factor ETV5 is associated with the IL-6 production pathway and inflammatory response in macrophages, indicating that the function of ETV5 in regulating inflammation may not be limited to ATMs in obesity." (PMID 34716308, 2021). "However, subjects with obesity with chronically elevated IL‐6 may not benefit from acute treatment." (PMID 32845580, 2020). "Moreover, the number of immunosuppressive T-regulatory, T-reg (CD4+CD25+Foxp3+) cells and concentrations of IL-6, IL-10, and C-reactive protein (CRP) were up-regulated in patients with severe COVID-19, suggesting that SARS-CoV-2 infection may lead to “over-immunosuppression” in the case of obesity." (PMID 32650509, 2020). "Noteworthy, no doubts are on the pro-inflammatory role of obesity, with all studies confirming an elevated concentration of EBC IL-6, IL-8 and ICAM-1 in obese than normal weight individuals." (PMID 31461988, 2019). "The observed trend between IL-6 (but not hs-CRP) and preeclampsia restricted to women with obesity and GDM warrants further study in larger cohorts." (PMID 30177064, 2018). "foz/foz mice developed obesity, hyperinsulinemia, diabetes, adipokine dysregulation and fatty liver, without increased serum or liver TNF-α or serum IL-6." (PMID 30873458, 2016). "The levels of CRP, IL-6, IL-17, and A-FABP in simple obesity and diabetes with or without obesity groups were obviously increased compared to those in the normal control group (P < 0.05)." (PMID 27819006, 2016). "Among the 3 groups, the diabetes with or without obesity groups had increased levels of CRP, IL-6, IL-17, and A-FABP compared to the simple obesity group (P < 0.05)." (PMID 27819006, 2016).
Obesity (continued). "Baseline biomarkers in 2000-4 (CRP, IL-6, sTNFR2, leptin, lipocalin 2 and A-FABP) had significantly positive correlation with indices of obesity WC and BMI while adiponectin had significant negative correlation." (PMID 24205276, 2013). "Insulin resistance in obesity is thought to be mediated via non-esterified fatty acids (NEFA) and proinflammatory factors including tumor-necrosis-factor-alpha (TNF-α), interleukin-6 (IL-6) and monocyte chemoattractant protein-1 (MCP-1)." (PMID 22984471, 2012). "There is an upregulation of inflammatory markers such as interleukin-6, interleukin-6 receptor and acute phase protein CRP in Acute Myocardial Infarction (AMI) patients but the exact mechanism linking obesity and inflammation is not known." (PMID 22891684, 2012). "Participants in the present study were hyperglycemic and obese, and they had normal TNF-α and IL-6 concentrations which suggest that the participants might have had increased oxidative stress secondary to high plasma glucose concentrations and their obesity not secondary to inflammation." (PMID 21554710, 2011). "Importantly, biomarkers such as CRP, IL-6, TNF-α, and leptin are frequently elevated in individuals with overweight or obesity independent of dietary exposures." (PMID 41010537, 2025). "Therefore, this study examined IL‐6, TNF‐α, and irisin responses to an acute bout of resistance exercise in children with PWS and compare their responses to children with and without obesity." (PMID 40243109, 2025). "This study revealed elevated IL-6 and TNF-α mRNA levels in the group with obesity compared to the one without, indicating that obesity alone may contribute to increased marker levels." (PMID 40004007, 2025). "A group effect (p = 0.011) and pairwise comparisons showed IL‐6 concentrations in children with PWS and children with obesity were greater than concentrations in children without obesity (0.94 ± 0.12 pg/mL and 0.95 ± 0.10 pg/mL vs. 0.52 ± 0.11 pg/mL; p = 0.038 and p = 0.020, respectively)." (PMID 40243109, 2025). "In contrast, recent research found that IL-6 was not but TNF alpha was affected by a walking exercise; however, the participants were postmenopausal women with obesity (68–72 years old), and this might have affected the study outcomes." (PMID 39199416, 2024). "In addition, unlike IL-6 and TNFα, Two-way ANOVA with interaction analysis revealed a strong interaction between low Flt3L expression levels and preterm birth in women with obesity." (PMID 39627409, 2024). "IL-1b, IL-6, and TNF were not significantly regulated in monocytes of people with obesity at the investigated time points but it would be interesting to take a closer look pro-inflammatory potential of the lipid droplet positive monocytes in further studies or in a time series-dependent analysis." (PMID 39050851, 2024). "For example, elevated levels of IL-6, IL-1β, and TNF-α mRNAs and reduced expression of brain-derived neurotrophic factor (BDNF) were found in the hippocampus of mice lacking leptin receptor (db/db mice), a genetic model of obesity." (PMID 37373230, 2023). "Consequently, obesity affected the levels of all cytokines in the systemic bloodstream, whereby the administration of OEA-DS promoted a decrease in the IL-6 and IL-1β levels, but not TNFα." (PMID 37892420, 2023). "Interestingly, the reduction in inflammatory cytokines following SIT in our group of men with overweight and obesity occurred despite having no changes in fat mass and having relatively low TNF‐a and IL‐6 at baseline." (PMID 35312183, 2022). "However, in a different study, leptin levels decreased in subjects with overweight or obesity who followed an ADF protocol, but adiponectin levels did not change, nor did other biomarkers of inflammation, including resistin, IL-6, or TNF-α." (PMID 36364915, 2022).